SOBP (sine oculis binding protein homolog)
Description:
Implicated in development of the cochlea.
Synonyms: JXC1; FLJ10159; MRAMS
Tractability: PROTAC: UniProt records ubiquitination sites on it; its protein half-life has been measured.
Gene: Protein-coding gene on chromosome 6 (107,490,073 to 107,661,306, forward strand). Ensembl gene ENSG00000112320.
Subcellular location (Human Protein Atlas): Nucleoplasm; Vesicles
Gene Ontology:
Molecular function: SUMO polymer binding; zinc ion binding
Biological process: cognition; animal organ development; inner ear morphogenesis; cochlea development
Cellular component: nucleus
Genetic constraint (gnomAD): Loss-of-function variants: 4 observed, 47.89 expected, observed/expected ratio (o/e) 0.0835, 90% interval 0.04 to 0.19. The synonymous counts are far from expectation, so gnomAD's model fits this gene poorly and the ratio says little. Missense variants: 1,088 observed, 1,122 expected, observed/expected ratio (o/e) 0.97, 90% interval 0.92 to 1.02. Synonymous variants: 583 observed, 488.27 expected, observed/expected ratio (o/e) 1.19, 90% interval 1.12 to 1.28.
Gene-disease validity (ClinGen):
ClinGen rates the evidence that SOBP causes each of these diseases.
syndromic intellectual disability (autosomal recessive): Limited. A intellectual disability that is part of a larger syndrome.
Homologues: Orthologues: chimpanzee SOBP (99% identical), macaque SOBP (99% identical), pig SOBP (98% identical), dog SOBP (94% identical), mouse Sobp (94% identical), rat Sobp (94% identical), tropical clawed frog sobp (78% identical), guinea pig SOBP (74% identical), rabbit SOBP (60% identical), zebrafish sobpa (57% identical), Drosophila melanogaster Sobp (24% identical). Paralogues in human: RAI2 (13% identical).
Diseases named in the same sentence as SOBP in open-access papers:
SOBP is named in the same sentence as 10 diseases in open-access papers, as found by Europe PMC text mining. Sharing a sentence is not in itself a finding about the gene and the disease. The quoted sentences say what the papers report.
Intellectual disability (6 papers, 2015 to 2025). "This gene is a SOBP (Sine Oculis-Binding Protein Homolog), and the protein encoded by this gene is involved in the development of the cochlea, and genetic defects are also related to intellectual disability." (PMID 39101784, 2024). "In addition, genes involved in learning and memory (ARHGAP39 and HERC1), intellectual disability (SOBP), or autism (NF1), whose mutations cause neurodevelopmental, behavioral, learning, and motor abnormalities, are repressed by exercise and normalized or slightly induced upon subsequent rest." (PMID 40725218, 2025). "These include regions with nearest protein-coding genes such as BCAS3, RFX3, SOBP, and PEX14, mutations in which have been linked to intellectual disability, neurological deficits, attention deficit hyperactivity disorder, or autism spectrum disorders." (PMID 41279093, 2025). "LHX2 also regulates brain development and is an activator of SOBP which has been observed to have strikingly specific expression in the limbic system, with disruption leading to abnormal cognition and intellectual disability." (PMID 27295951, 2016).
deafness (1 paper, 2015). An inherited or acquired condition characterized by the complete loss of the ability to hear from one or both ears. "The locus contained FOXO3 and SOBP, known to cause deafness in mice, but Sanger sequencing and careful assessment did not identify any variation in these genes." (PMID 26197441, 2015).
leukemia (1 paper, 2025). A malignant (clonal) hematologic disorder, involving hematopoietic stem cells and characterized by the presence of primitive or atypical myeloid or lymphoid cells in the bone marrow and the blood. "Similarly, SIX3 and SOBP regulate transcription and development, influencing leukemia cell differentiation." (PMID 40506993, 2025).
ovarian carcinoma (1 paper, 2021). A malignant neoplasm originating from the surface ovarian epithelium. "Our study establishes a novel MEG8/miR‐378d/SOBP axis in the development and prognosis of ovarian cancer, and the triple sub‐network probably affects the progression of ovarian tumor by regulating cytokines pathway." (PMID 33742531, 2021).
cancer (1 paper, 2021). A tumor composed of atypical neoplastic, often pleomorphic cells that invade other tissues. "We performed a pan‐cancerous analysis of mRNA expression by using Oncomine and TIMER databases, the results showed SOBP was a lower expression in various human cancers, including OC." (PMID 33742531, 2021).
tumor (1 paper, 2021). "Meanwhile, RIPK4 and SOBP mRNA expression was associated with the tumor pathological stage, which was consistent with their survival outcomes." (PMID 33742531, 2021). "In summary, we detected six DEGs (RIPK4, SCNN1A, SLC4A11, ELF3, CLDN4, and SOBP) which can serve as tumor markers for the diagnosis and prognosis of OC." (PMID 33742531, 2021). "Next, we investigated the correlation among the transcription of SOBP and the rank of tumor‐infiltrating immune cells in more detail, based on the immune marker genes expression in OC tissues from the TIMER databases." (PMID 33742531, 2021). "We then noticed that low SOBP expression correlated with elevated infiltration of generally immune cell types in OC and showed a significant correlation with tumor purity." (PMID 33742531, 2021). "According to the mRNA expression level of SOBP, we obtained nine types of tumor‐infiltrating lymphocytes in OC tissues, containing B cells, CD8+ T cells, Th 1, Treg, T cell exhaustion, macrophages (TAM, M1, and M2), neutrophils, dendritic, and natural killer cells from TIMER." (PMID 33742531, 2021). "Altogether, the MEG8/miR‐378d/SOBP competing endogenous RNA (ceRNA) axis could be the potential mechanism in affecting tumor progression and prognosis of OC." (PMID 33742531, 2021). "In addition, we reported the novel MEG8/miR‐378d/SOBP ceRNA subnetwork first, and speculate that it may act a crucial part in the tumor progression and immune function of OC by regulating the cytokines pathway." (PMID 33742531, 2021). "Therefore, under a comprehensive analysis and previous reports, we establish the MEG8/miR‐378d/SOBP axis and speculate that it may act a crucial role in the tumor progression and immune function of OC by regulating the cytokines pathway." (PMID 33742531, 2021).
SOBP also shares sentences with these, for which no sentence is quoted: Alzheimer disease (1 paper); attention deficit-hyperactivity disorder (1); autism (1); cardiac arrhythmia (1).